AR (androgen receptor)
Diseases named in the same sentence as AR in open-access papers (continued):
Sharing a sentence is not in itself a finding about the gene and the disease.
prostate carcinoma (continued). "We have shown that persistent AR activity promotes cellular senescence in prostate cancer and in normal prostate epithelial cells." (PMID 22403609, 2012). "Consistent with Skp2’s role as a downstream effector of androgen receptor in mediating proliferation in prostate cancer cells, its expression level in androgen-responsive LNCaP cells is substantially higher than in androgen-independent PC-3 and DU-145 cells." (PMID 23071779, 2012). "The screen identified kinases previously shown to regulate prostate cancer cell growth and AR activity, including the ribosomal S6 kinase (RPS6KA3 or RSK)." (PMID 22761715, 2012). "The recent advances in the medical management of advanced prostate cancer include successful translation and development of novel agents that target different components of the androgen-AR axis." (PMID 22956944, 2012). "Androgen receptor (AR) signalling is critical to the initiation and progression of prostate cancer (PCa)." (PMID 23095762, 2012). "Androgen receptor is a central player throughout development of prostate cancer, even after androgen deprivation therapy." (PMID 22849360, 2012). "The progression of prostate cancer occurs via the alternation of the normal androgen axis by the dysregulation of AR activity through signal transduction cascades, alterations in AR coregulator expression, and mutations in AR." (PMID 23145053, 2012). "In our study, tanshinones (TI, TIIA and CT) at sub- and low micromolar concentrations suppressed cell growth and AR-dependent transcription in AR-responsive prostate cancer cells in a concentration-dependent manner." (PMID 23202971, 2012). "Prostate cancer (PCa) is dependent on androgen receptor signaling and aberrations of the PI3K-Akt-mTORC1 pathway mediating excessive and sustained growth signaling." (PMID 22891897, 2012). "It has been reported that EGF is capable of inducing AR transcription and protein expression in androgen-independent prostate cancer cells." (PMID 22922989, 2012). "Akt3 enzymatic activity was approximately 20-60-fold higher in AR-negative PC-3 and DU-145 cells compared to the AR-positive LNCaP prostate cancer cells." (PMID 22347457, 2012). "The androgen receptor (AR), a ligand-activated member of the nuclear receptor superfamily, plays a critical role in the male phenotype and prostate cancer biology." (PMID 23034120, 2012). "For example, inhibition of PI3K in prostate cancer cells activates signaling by the androgen receptor (AR) and inhibition of the AR, in turn, activates AKT signaling by reducing levels of the AKT phosphatase PHLPP." (PMID 22248929, 2011). "Recent studies have identified a long-range activation of FKBP5 transcription in prostate cancer cells by the AR via distal intronic enhancers." (PMID 21119664, 2011). "Using p285PB-Luc as a reporter, we confirm that Pax6 represses AR-mediated transactivation in LNCaP prostate cancer cells." (PMID 21935435, 2011). "PCNCR1 is expressed as an intronless, ~13 kb transcript with a potential role in trans-activation of androgen receptor (AR), a key player in prostate cancer progression." (PMID 21489289, 2011). "In the same study, over-expression of cyclin D2 induced anti-proliferative effects on LnCap cells, but not PC3 cells, suggesting that the inhibitory effects of cyclin D2 is limited to AR-dependent prostate cancer cells." (PMID 22303414, 2011). "AR transcriptional activity is required for the maintenance and growth of the prostate which forms the rationale for androgen ablation therapies for prostate cancer." (PMID 21909421, 2011). "HDAC inhibitors have been noted to have greater antiproliferative effects on AR-positive prostate cancer cells than their AR-negative counterparts and inhibit xenograft growth in both castration-sensitive- and resistant models." (PMID 22191037, 2011).
prostate carcinoma (continued). "The AR-rich relapsed prostate cancer cells will then undergo G1 cell cycle arrest and/or apoptosis, causing the regression of tumor and decrease of serum PSA level." (PMID 21859492, 2011). "Current thinking attributes prostate cancer growth and development to stimulation of the androgen receptor even at low-plasma testosterone levels." (PMID 21285990, 2011). "Immunostaining and Western blot with the anti-p44/WDR77 antibody revealed that p44/WDR77 is cytoplasmic in AR-positive prostate cancer LNCaP and 22RV1 cells, in agreement with our previously reported data." (PMID 21789256, 2011). "In summary, our AR-response profiling revealed that a considerable fraction of AR pathway genes were up-regulated in primary prostate cancer compared to normal prostate and down-regulated in metastasis." (PMID 21829708, 2011). "Although we are broadly aware of the specifics of the genomic actions of AR in prostate cancer cells, relatively little is known regarding the gene targets of functional AR in prostate stromal cells." (PMID 21267466, 2011). "Together these data support that AR and FUS associate within the same complex in prostate cancer cells." (PMID 21909421, 2011). "PC3 prostate cancer cells, devoid of functional AR, were co-transfected with each of the Gal4 fusion constructs, and a reporter gene containing the minimal Gal4-binding sites (p5×Gal4UAS-TATA-luciferase)." (PMID 21909421, 2011). "The high efficacy of VN/124-1 in several prostate cancer models is believed to arise from its ability to downregulate the AR as well as competitively block androgen binding." (PMID 22111003, 2011). "A more recent investigation has demonstrated that forced expression of AR, in a subline of a metastatic androgen-dependent prostate cancer cell line, led to increased invasion." (PMID 22164169, 2011). "FlnA and its proteolytic fragments directly interact with AR, thereby modulating nuclear translocation and transcriptional action of AR as well as androgen dependence of prostate cancer LNCaP cells." (PMID 21359179, 2011). "Cell-cell signaling and the androgen receptor pathway continue to be appropriate and promising targets for new agents in men with prostate cancer." (PMID 22110986, 2011). "Regardless of the mechanism, this experimental outcome further supports the idea that androgen action in AR-positive fibroblasts has consequences for prostate cancer growth." (PMID 21267466, 2011). "Here, we examined the effect of ZMIZ1 on different AR polyQ vectors in the presence of antagonists in the prostate cancer cell line, DU145." (PMID 21949845, 2011). "The p44/WD77 protein contains 342 amino acid residues and seven putative WD-40 repeats, interacts with androgen receptor (AR), and regulates expression of a set of androgen target genes in the prostate gland and in prostate cancer." (PMID 21789256, 2011). "For instance, reverse-engineering of gene networks derived from expression profiles was used to study prostate cancer, from which the androgen-receptor (AR) emerged as the top candidate marker to detect the aggressiveness of prostate cancers." (PMID 21352556, 2011). "In this study, both the AR+ and AR- prostate cancer cells were generated under the effects of persistent Hedgehog signalling activation in the mouse model." (PMID 21241512, 2011). "To characterize the expression profile of androgen receptor target genes in prostate cancer cells, we used expression microarray analysis on the PC346 cell line panel incubated with the androgen analogue R1881 or the antiandrogen OH-flutamide." (PMID 21829708, 2011). "To this end, we employed a proteomic approach and identified novel endogenous AR interaction partners in prostate cancer cells that include members of a group of proteins called FET/TET." (PMID 21909421, 2011).
prostate carcinoma (continued). "For example, during prostate carcinogenesis, the regulatory function played by the androgen receptor is often converted from a growth suppressor to an oncogene thus promoting prostate cancer cell survival and eventual metastasis." (PMID 21378414, 2011). "A number of AR inhibitors are currently used for prostate cancer, and their safety in a female patient population has been demonstrated in studies of breast and ovarian cancers." (PMID 21457548, 2011). "Much evidence therefore exists for AR functioning as a ligand-dependent tumor suppressor in prostate cancer cells when it is expressed at high levels and is fully activated." (PMID 21859492, 2011). "In contrast, images captured from prostate cancer-derived LNCaP cells or Cos cells ectopically expressing wt hAR show that 10 nM R1881 clearly induces nuclear translocation of AR." (PMID 21359179, 2011). "On the other hand, various chemical analogs of curcumin, including ASC-J9 and its derivatives, have been shown to inhibit prostate cancer cell proliferation by enhancing AR degradation or by acting as the pure AR antagonist." (PMID 21859497, 2011). "The transcription factor Pax6 has recently been reported to act as a repressor of AR and to be hypermethylated in prostate cancer cells." (PMID 21935435, 2011). "The scope of pathophysiologically relevant protein-protein interaction involving AR in prostate cancer cells is, however, not fully known." (PMID 21909421, 2011). "Recent studies demonstrated the continued role of the AR in driving PC cell growth even in the presence of low levels of circulating androgens and the emergence of a castrate-resistant prostate cancer (CRPC) phenotype." (PMID 22191037, 2011). "The androgen receptor (AR) is a transcriptional activator that plays important roles in the development of advanced stage (androgen-independent) prostate cancer." (PMID 21637378, 2011). "Androgen receptor (AR) controls male morphogenesis, gametogenesis and prostate growth as well as development of prostate cancer." (PMID 21359179, 2011). "It is clear that a more detailed understanding of the AR alterations in the evolution of androgen-refractory prostate cancer is needed to help drive the development of potential new therapies." (PMID 22164169, 2011). "The AR is critical for the maintenance of normal prostate function and the development and progression of prostate cancer, and is the main target in current treatments for prostate cancer." (PMID 21980513, 2011). "Our preliminary results showing that ZEB1 mRNA levels increase in response to androgen treatment in the 22RV1 and PC3/AR prostate cancer cell lines have been published." (PMID 22190929, 2011). "Androgens drive the onset and progression of prostate cancer (PCa) by modulating androgen receptor (AR) transcriptional activity." (PMID 22194994, 2011). "Recent discoveries revealed a transcription-independent function of androgen receptor that is essential for prostate cancer cell viability and, therefore, is an ideal target for anticancer treatment." (PMID 22228887, 2011). "Zebularine caused a dose-dependent inhibition of proliferation in both LNCaP and PC3 prostate cancer cells (p<0.0001), suggesting that Zebularine has a similar AR-independent growth inhibitory mechanism of action on prostate cancer cells as 5-aza-CdR." (PMID 21980513, 2011). "In particular, 5 of these genes are involved in prostate cancer progression and most of them are AR (androgen receptor) regulated." (PMID 21266046, 2011). "DHT-induced prostate cancer cellular contact-independent growth is also blocked by Sirt1, providing a direct functional link between Sirt1 and the AR, which is a critical determinant of progression of human prostate cancer." (PMID 21549004, 2011). "Ack1 also phosphorylates androgen receptor (AR), increasing the levels of phosphorylated AR in prostate cancer and promoting AR-mediated gene transcription." (PMID 21637378, 2011).
prostate carcinoma (continued). "Relating these examples specifically to prostate cancer, it has been demonstrated that β-catenin can interact with androgen receptor and increase its transcriptional activity, hence contributing to prostate cancer progression." (PMID 21672215, 2011). "The androgen receptor (AR) and androgens have a central role in development and maintenance of the male reproductive system and in the etiology of prostate cancer, the most commonly diagnosed invasive cancer in men in the USA and other western countries." (PMID 21935435, 2011). "Our findings raise an interesting question regarding the potential significance of ZMIZ1 effects on AR mediated transcription in prostate cancer pathogenesis and particularly in disease progression during androgen deprivation therapy." (PMID 21949845, 2011). "Our preliminary studies revealed that it was indeed regulated by androgen in both PC3/AR and 22Rv1 prostate cancer cell lines." (PMID 22190929, 2011). "FK506 binding protein 5 can form a complex with AR to enhance AR transcriptional activity in prostate cancer." (PMID 21119664, 2011). "The deregulated AR signaling is commonly observed in cancer cells, especially prostate cancer cells." (PMID 22200028, 2011). "Next we evaluated the role of the AR pathway in prostate cancer development and how it is modulated during cancer progression by linking our androgen-regulated gene signature to seven previously published microarray databases on clinical tumor samples." (PMID 21829708, 2011). "It is generally accepted that the AR pathway accounts for the tumor growth in most prostate cancer patients even under hormonal ablation therapy." (PMID 21829708, 2011). "Critical to androgen sensitive and castrate resistant prostate cancer growth and survival is the transcriptional activity of the AR." (PMID 22087262, 2011). "The current literature has shown that the expression of AR and its downstream target genes remain at high levels in castration resistant prostate cancer." (PMID 21949845, 2011). "The androgen receptor (AR) signaling pathway, which is essential for prostate development and normal function, is also central to prostate cancer's pathogenesis and progression." (PMID 22194926, 2011). "Another oncogene, VAV3, known to regulate cell growth and androgen receptor activity in prostate cancer, also showed a significant increase with LH addition." (PMID 21711548, 2011). "Treatment for advanced prostate cancer currently involves hormone therapies that lower serum testosterone and antagonize the transcriptional capabilities of the androgen receptor (AR) by targeting its ligand binding domain." (PMID 22087262, 2011). "Members of the canonical Wnt pathway, including Wnt-3a and Wnt-1 and β-catenin, have been shown to be up-regulated in metastatic prostate cancer and β-catenin and AR have been shown to co-localize in the nucleus in advanced prostate cancer samples." (PMID 24212771, 2011). "Nuclear import of isolated NLS signals is defective in AR-positive prostate cancer (LNCaP and 22RV1) cells, leading to sequestering of p44/WDR77 into cytoplasm and relieve p44/WDR77-mediated growth inhibition." (PMID 21789256, 2011). "Statins decrease androgen receptor protein expression and induce apoptosis and cell growth arrest in cultured prostate cancer cells, and suppress tumor growth in prostate cancer mice xenografts." (PMID 22202492, 2011). "AR plays a crucial role in prostate cancer progression and is known to regulate the TMPRSS2 promoter, which constitutes the regulatory part of the TMPRSS2/ERG fusion." (PMID 21747944, 2011). "In general, from these analyses we can conclude that the AR pathway is modified and still able to respond to stimuli, in the majority of therapy-resistant prostate cancer cells subjected to long-term androgen ablation." (PMID 21829708, 2011).
prostate carcinoma (continued). "Tokai Pharmaceuticals initiated ARMOR1 (Androgen Receptor Modulation Optimized for Response 1) phase 1/2 trials in castrate-resistant prostate cancer patients on November 5, 2009." (PMID 22111003, 2011). "WPMY-AR cells express AR mRNA and protein at a level comparable with androgen-sensitive LNCaP prostate cancer cells." (PMID 21267466, 2011). "ADAM10 has a role in androgen receptor nuclear translocation and has been shown to translocate to the nuclear and the perinuclear region during prostate cancer pathogenesis and progression." (PMID 21569301, 2011). "AR was observed only in the androgen-dependent LNCaP prostate cancer cells, which is consistent with the reported expression of AR when these cells were first characterized." (PMID 21619605, 2011). "The regression of tumors can continue for weeks or months before the prostate cancer cells adapt to the androgenic suppression, possibly by down-regulating AR." (PMID 21859492, 2011). "The Raf family of serine/threonine kinases and the MAP kinase (MAPK) pathway are heavily implicated in prostate cancer as activation of the Raf/MAPK pathway increases prostate cancer cell growth both AR-dependent and -independent under in vitro conditions." (PMID 21559022, 2011). "Increase in AR mRNA and protein is both necessary and sufficient to convert prostate cancer growth from a hormone-sensitive to a hormone-refractory stage, and is dependent on a functional ligand-binding domain." (PMID 21859492, 2011). "The length of polyQ tracts has been suggested to alter AR transcriptional activity in prostate cancer along with other endocrine and neurologic disorders." (PMID 21949845, 2011). "Prostate cancer stem cells are shown to be androgen independent and lack expression of a functional androgen receptor which renders them immune to androgen deprivation therapy (ADT)." (PMID 21779382, 2011). "The androgen receptor (AR) has a central role in development and maintenance of the male reproductive system and in the etiology of prostate cancer." (PMID 21935435, 2011). "Data herein demonstrate that tcf8 is induced by dihydrotestosterone (DHT) in the human PC-3/AR prostate cancer cell line and that this induction is mediated by two androgen response elements (AREs)." (PMID 22190929, 2011). "While a role of NcoA4 in proliferation has been described in prostate cancer cell lines, these effects are dependent upon androgen and are likely due to NcoA4 functioning as an AR coregulatory protein." (PMID 21814571, 2011). "Overall, this was first line of evidence that ZMIZ1, rather than ZMIZ2 or ARA70, enhances the ligand-induced transactivation of AR with shorter polyQ tract in prostate cancer cells." (PMID 21949845, 2011). "Studies have shown that β-catenin interacts with the androgen receptor, perhaps further indicating its relevance to prostate cancer progression." (PMID 21949592, 2011). "This latter category of genes affected by androgens was consistent with our findings that conditioned medium from androgen-stimulated WPMY-AR cells more support prostate cancer cell growth than from androgen-stimulated control cells that lack AR." (PMID 21267466, 2011). "The fusion gene can be up-regulated at a late time by reactivating AR in castration-resistant prostate cancer." (PMID 21731703, 2011). "Androgens are known to have a role in the progression of prostate cancer, in which a crosstalk between the androgen receptor and canonical Wnt pathways has been identified at several levels in these signalling pathways." (PMID 21468052, 2011). "Androgens are well known to influence cell behaviour in prostate cancer, and a role for testosterone in β-catenin signalling in prostate cancer is suggested by data showing that androgen receptor activation potentiates Wnt signalling." (PMID 21468052, 2011). "The status of histone lysine methylation has been shown to be important for AR signaling, and several histone demethylase proteins are upregulated in prostate cancer." (PMID 22111003, 2011).